NF2 (NF2, moesin-ezrin-radixin like (MERLIN) tumor suppressor)
Diseases named in the same sentence as NF2 in open-access papers (continued):
Sharing a sentence is not in itself a finding about the gene and the disease.
meningioma (continued). "Meningioma‐relevant mutations were present in 90/126 (71.4%) specimens including NF2, TRAF7, KLF4, SMO, AKT1,TERT promotor, ARID,SUFU, and PIK3CA mutations in similar frequencies compared to previous studies." (PMID 35213082, 2022). "CREBBP, PIK3CA (R108H), PIK3R1, BRCA1, and SMARCB1 are the most represented mutations; unfortunately, none of these mutations can predict the rate of recurrence in NF2-mutated meningiomas." (PMID 35892898, 2022). "TRAF7 is the most common somatic mutation in non-NF2 meningiomas, present in ~ 25% of sporadic tumors." (PMID 34846640, 2022). "Molecular analyses have shown that meningiomas can be widely divided into NF2-mutated and non-NF2-mutated, but the clinical implications of this finding are unclear." (PMID 36232992, 2022). "Germline mutations are well-established drivers of meningioma formation, especially those arising in the context of genetic diseases such as neurofibromatosis type II (NF2), Gorlin and Cowden syndromes." (PMID 34846640, 2022). "The only trial to enroll meningioma patients alone is A071401, a Phase 2 trial of SMO/AKT/NF2/CDK inhibitors in patients with progressive meningiomas harboring corresponding mutations in the respective signaling pathway (NCT02523014)." (PMID 35936751, 2022). "Alterations in the NF2 gene, the most common genetic disturbance associated with meningiomas, were evenly distributed across grades and comprised approximately 40% of the total meningioma cohort." (PMID 35299730, 2022). "NF2 encodes for the tumor suppressor protein merlin, the loss of which is a well-studied driver mutation commonly implicated in high-grade meningiomas." (PMID 36686824, 2022). "Merlin-intact meningiomas were characterized by gain of function in chromosome 5, loss of function in chromosome 6p, and intact NF2 expression, with the best overall survival among the three groups." (PMID 36686824, 2022). "Co-mutations in NF2-mutant meningiomas included SMARCB1 (n = 3) and PTEN (n = 1) mutations (online resource)." (PMID 35943573, 2022). "The genetic landscape of the most common subtype of meningioma involves mutation or copy loss of the Neurofibromin 2 (NF2) gene in approximately 50% of cases." (PMID 35996584, 2022). "Chromosome 14q loss showed the largest difference between atypical and low grade NF2-mutated meningiomas." (PMID 34846640, 2022). "For instance, we showed in a patient with five NF2-loss meningiomas, one of the tumors acquired the pathogenic SMARCB1 mutation." (PMID 35568945, 2022). "In light of the neuroanatomically mutually exclusive incidence of some specific mutations in meningiomas, NF2 is a particularly attractive target for supratentorial NSBM." (PMID 36497370, 2022). "All three NF2-mutated meningiomas had transitional histotype, confirming the previously reported association between NF2 mutations and fibrous, transitional or atypical histotypes." (PMID 35049691, 2022). "Reports on non-NF2 mutated meningioma showed relatively low frequency of genomic alterations per patient." (PMID 35163107, 2022). "Brigatinib, an inhibitor of multiple tyrosine kinases, was capable of stopping the growth of NF2-deficient xenograft meningiomas for the inhibition of multiple tyrosine kinases, including EphA2, Fer, and focal adhesion kinase 1 (FAK1)." (PMID 35712491, 2022). "Loss of NF2 protein (Merlin) expression due to mutations in the NF2 gene is one of the most common causes of benign brain tumors (including schwannomas and meningiomas)." (PMID 36611803, 2022). "This system was first used to better understand the role of allelic loss and/or mutation in the NF2 gene at chromosome 22q (the main driver event in sporadic meningiomas)." (PMID 34359639, 2021). "Neurofibromin 2 (NF2) mutation is the first characterized alteration in meningioma and is observed in approximately 80% of high grade meningiomas, suggesting that it is potentially a prognostic biomarker." (PMID 33807688, 2021).
meningioma (continued). "Given the strong and prevalent association between NF-2 mutations and meningiomas, some authors recommend germline NF-2 screening be done prior to meningioma resection in patients younger than 30 years old or with multiple central nervous systems tumors." (PMID 34638590, 2021). "More interestingly, almost all NF2 fusions were enriched in subtype 3, suggesting that NF2 was associated with meningioma progression, which is consistent with the previous study." (PMID 33807688, 2021). "To date, successful orthotopic transplant models have only been developed for NF2-associated meningioma." (PMID 34072574, 2021). "Other research regarding bevacizumab, a vascular endothelial growth factor (VEGF) inhibitor, has shown promise for NF2-associated schwannomas, meningiomas, and ependymomas." (PMID 34944845, 2021). "We comprehensively evaluated associations among tumor location, pathological diagnosis (histological type), and genetic alterations including AKT1, KLF4, SMO, POLR2A, and NF2 mutations and 22q deletion in 269 meningioma cases." (PMID 33772057, 2021). "Chromosomal studies have shown that the majority of NF-2 mutated meningiomas are accompanied by marked chromosomal instability that produced copy loss or duplication of a multitude of other chromosomes." (PMID 34638590, 2021). "Together with the high frequency of NF2 alterations it can be concluded that pediatric meningiomas are mainly driven by loss of this tumor suppressor." (PMID 34495383, 2021). "Bilateral vestibular schwannomas are pathognomonic for NF2 and the condition is also commonly associated with the development of multiple meningiomas." (PMID 34264955, 2021). "In turn, the frequency of non-synonymous genetic variants that affected individual genes in these three cytogenetic subgroups of meningiomas revealed different mutational profiles among them for the NF2, SMO, and POLR2A genes." (PMID 34868937, 2021). "High-grade meningiomas are nearly exclusively associated with NF-2 mutations or q22 deletions, with only 5% of high-grade meningiomas harboring mutations in mTOR, Sonic hedgehog or other known tumorigenic pathways." (PMID 34638590, 2021). "In large-scale genomic studies of meningioma, HGMs were in some studies exclusively related to pathogenic variants in NF2, associated with mutations in the TERT promoter." (PMID 34778063, 2021). "Similar to ALK-IN-1, brigatinib inhibited viability of NF2-deficient Syn5 arachnoidal and Ben-Men-1 meningioma cells and two independent primary meningioma cell lines with NF2 loss (MN612 and MN621)." (PMID 34264955, 2021). "Focusing on the molecular aberrations in the multiple meningiomas found in NF2 is still in the process of being unraveled as the genetic profiling of NF2 associated meningiomas is ongoing." (PMID 33445724, 2021). "In NF2, therapy of brain tumors precedes therapy of peripheral tumors since associated vestibular schwannomas, ependymomas and meningiomas lead to more severe complications." (PMID 33863389, 2021). "In these reports, NF2 mutations and/or loss of chromosome 22 are predominant in meningiomas originating from the cerebral convexity and cerebellar dura and in the spinal canal." (PMID 33772057, 2021). "While the vast majority of adult patients with meningiomas presents with sporadic tumors, pediatric patients are more commonly affected by an underlying tumor predisposition syndrome, mainly NF2." (PMID 34495383, 2021). "Similar to meningiomas arising in the setting of germline NF2 mutations, radiation induced meningiomas are characterized by NF2 inactivation." (PMID 34495383, 2021). "NF2 mutation with chromosome 22q loss was only detected in subtype 2 while almost all meningiomas containing chromosome 1p loss with NF2 mutation or chromosome 22q loss were clustered in subtype 3." (PMID 33807688, 2021). "FAK inhibitor GSK2256098 is currently under investigation for its role in treating NF-2 mutation-associated meningiomas (NCT02523014)." (PMID 34638590, 2021).
meningioma (continued). "In turn, recurrent mutations in the TIGD1 gene were found across all cytogenetic subgroups of meningiomas including both NF2-mutated and wild-type tumors." (PMID 34868937, 2021). "Evidence shows that the presence of nuclear YAP is strongly associated with mutations in NF2 in sporadic tumors that derive from the nervous system, such as schwannomas and meningiomas." (PMID 33805359, 2021). "The recognition of the association between meningioma formation and neurofibromatosis 2 (NF-2) gene inactivation over three decades ago has opened the door to the identification of countless genetic alterations of a growing number of non-NF-2 genes." (PMID 34638590, 2021). "Somatic Nf2 loss after subarachnoid or subdural viral injection of Cre recombinase into newborn Nf2 flox/flox conditional knockout mice result in meningioma." (PMID 34072574, 2021). "As many as 70% of NF-2-associated meningiomas of the anterior falx have SMARCB1 co-mutation, compared to 16% co-mutation rate in tumors of other locations." (PMID 34638590, 2021). "Other numerous genetic alterations, including extensive chromosome losses and gains together with mutations in genes other than NF2, have been recurrently reported in meningiomas." (PMID 34868937, 2021). "The development of a molecularly driven trial of patients given targeted therapy based on their AKT1, SMO, and NF2 pathogenic variant status is an ideal example of the future for clinical trials in patients with meningioma (NCT02523014)." (PMID 33262459, 2021). "To date, models of NF2-associated ependymoma remain yet to be generated whereas genetically engineered mouse strain of meningiomas have been." (PMID 34072574, 2021). "The mechanism of tumorigenesis in NF2 has yet to be fully elucidated, although loss of heterozygosity involving allelic loss of NF2 is thought to be a likely mode, as evidenced by work on skin tumors, vestibular schwannomas, and meningiomas in NF2 patients." (PMID 33445724, 2021). "On a molecular level, tumors can be roughly dichotomized as NF2 (neurofibromatosis type 2) and non-NF2-mutated meningiomas, and NF2 is the main identified driver mutation in atypical meningiomas." (PMID 34209798, 2021). "Neurofibromatosis type 2 (NF2) is the most common and first identified driver gene associated with meningioma." (PMID 33262459, 2021). "At present, it can be clarified that NF2 gene mutation located on chromosome 22 will lead to the occurrence of meningioma." (PMID 33673851, 2021). "This has traditionally been associated with convexity meningiomas in patients with NF2, a tumor suppressor syndrome where patients have a 50–75% lifetime risk of developing a meningioma." (PMID 33262459, 2021). "Loss of chromosome 1q along with Neurofibromin 2 (NF2) mutation or loss of chromosome 22p is exclusively presented in subtype 3 meningioma." (PMID 33807688, 2021). "The majority of convexity and parasagittal meningiomas are associated with NF-2 mutants or chromosome 22 deletions." (PMID 34638590, 2021). "Lapatinib showed some activity in a small number of patients with NF2-associated progressive meningiomas." (PMID 34072574, 2021). "Progestine-associated meningiomas, which are generally grade 1 and 2, present NF2 alteration only in 7.5% of cases, while a PIK3CA mutation can be found in 35% of cases." (PMID 34679551, 2021). "Germline mutations in NF-2 cause the inherited genetic disorder neurofibromatosis type 2, characterized by the development of schwannomas and meningiomas." (PMID 34638590, 2021). "Forty-four of the 49 patients (89.8%) with fibrous type and 22 of the 25 patients (88.0%) with WHO grade II meningiomas harbored an NF2 mutation or 22q loss." (PMID 33772057, 2021). "Ongoing trials investigate MEKi selumitinib and cobimetinib for NF2-tumor-associated hearing loss and MEKi trametinib in combination therapy for aggressive and recurrent meningiomas." (PMID 33863389, 2021).
meningioma (continued). "NF2 mutation predispose to the development of meningiomas, and it seems to be associated with fibroblastic/transitional meningiomas." (PMID 34679551, 2021). "In line with these later findings, in vitro studies also indicate that NF2-mutated meningiomas are associated with a slower growth than NF2 wild-type tumors." (PMID 34868937, 2021). "This is in accordance with other studies reporting NF2 as the only gene frequently mutated in atypical meningiomas." (PMID 33670055, 2021). "Neurofibromin 2 (NF2) was the first gene to be associated with an increased risk to develop meningioma." (PMID 34868937, 2021). "NF-2 is the most commonly associated gene associated with meningioma oncogenesis, with 50–60% of meningiomas having either an inactivating NF-2 mutation or monosomy of chromosome 22 with resultant loss of an NF-2 gene." (PMID 34638590, 2021). "On comparing different skull-base locations, most non-NF2 meningiomas were located on the medial skull base, whereas those on the lateral and posterior skull base harbored NF2 mutations or loss of chromosome 227,8,12,16–19." (PMID 33772057, 2021). "A common molecular alteration in meningiomas is 22q12 chromosome deletion that encodes for the tumor suppressor gene Merlin (also called neurofibromin 2, NF2), present in about half of all tumors." (PMID 34679551, 2021). "Neurofibromatosis Type 2 (NF2) is an autosomal dominant genetic syndrome caused by mutations in the NF2 tumor suppressor gene resulting in multiple schwannomas and meningiomas." (PMID 34264955, 2021). "Using this approach, we have identified for the first time, single and combinatorial agents that positively impact the treatment of both schwannomas and meningiomas associated with NF2." (PMID 34264955, 2021). "Of 12 samples harbouring DMD mutations, 11 had alterations in both copies of the neurofibromin 2 (NF2) gene, the most commonly mutated gene in meningioma, which encodes the tumour suppressor protein merlin." (PMID 33188621, 2021). "Germline mutations in NF2 cause Neurofibromatosis type 2, a cancer syndrome characterized by the development of schwannomas, meningiomas and ependymomas." (PMID 34424918, 2021). "Based on these molecular features, several clinical trials in NF-2 wild type meningiomas, including targeted therapy for actionable mutations in PIK3CA, SMO, and AKT1 are ongoing (NCT02523014)." (PMID 33611710, 2021). "Lack of recurrent NF2 mutations among our WHO grade 1 meningiomas, as well as in most series reported in the literature, suggests that sporadic meningioma cells frequently acquire NF2 mutations randomly, in both WHO grade 1 and higher-grade tumors." (PMID 34868937, 2021). "Mutations of the NF2 gene are strongly associated with NF2 diagnosis, leading to benign proliferative conditions such as vestibular schwannomas and meningiomas." (PMID 33445724, 2021). "In patients with NF2, those with truncating NF2 mutations towards the 5′end of the gene were associated with a higher prevalence and lifetime risk of meningioma." (PMID 33262459, 2021). "Apart from NF2 alterations in sporadic meningiomas, various oncogenic mutations in KLF4, SMO, TRAF7, PIK3CA, AKT1 and POLR2A are also found to be clinically actionable genetic events in meningiomas." (PMID 34722286, 2021). "More interestingly, variety of somatic mutations were presented in subtype 1 meningioma, except for NF2 mutation and chromosome 1p and chromosome 22q loss." (PMID 33807688, 2021). "One previous study found some novel gene fusions involved in NF2, the most common mutation in meningioma." (PMID 33807688, 2021). "Given the fact that brigatinib caused tumor shrinkage in both NF2 associated schwannoma and meningioma, a clinical trial was initiated to assess the therapeutic effectiveness of brigatinib in NF2-associated tumors (ClinicalTrials.gov: NCT04374305)." (PMID 34264955, 2021).
meningioma (continued). "The few pediatric tumors clustering with adult malignant (light green) or benign NF2-mutated tumors (light blue) were an anaplastic meningioma, an atypical meningioma, and a fibroblastic meningioma." (PMID 34495383, 2021). "NF2 inactivation has been linked to increased CIN in meningiomas, but for the first time, we report that its copy number deletion is potentially associated with high CIN level in GIST." (PMID 34594355, 2021). "Mice were first injected with the human NF2-deficient Ben-Men-1 meningioma cells and then treated with either 120 mg/kg/qd MK-2206, 50 mg/kg/qd brigatinib, or the combination." (PMID 34264955, 2021). "Neither tumor contained mutations in additional genes associated with meningioma (such as NF2 and AKT1) or malignancy, strongly implicating BAP1 inactivation in disease pathogenesis." (PMID 34504799, 2021). "The high frequency of this mutation can create a subdivision of meningiomas into NF2 and non-NF2 mutated." (PMID 34679551, 2021). "Among the NF2-mutated meningiomas, two cases, resected from male patients and located at the convexity, showed 1p and/or 22q deletion, and ARID1A or FBXW7 mutation." (PMID 33670055, 2021). "As validation of the observed kinase targets in Syn1 and Syn5 cells, 2-hour incubation of 10 and 100nM brigatinib was performed prior to kinome profiling in an NF2-deficient meningioma cell line Ben-Men-1." (PMID 34264955, 2021). "Somatic loss of NF2 has also been implicated in spontaneous human OSAs, schwannomas, meningiomas, mesothelioma, glioblastoma, breast, colorectal, skin, clear renal cell, prostatic and hepatic carcinomas." (PMID 33556121, 2021). "In large-scale genomic studies of meningioma, higher grade (WHO grade II and III) meningioma were in some studies exclusively related to pathogenic variants in NF2, associated with mutations in the TERT promoter, and deletion of 1p and CDKN2A." (PMID 33262459, 2021). "Loss of chromosome 22 has been widely implicated in the pathogenesis of meningioma, sharing a common pathway for tumorigenesis with NF2 patients due to the presence of neurofibromin on chromosome 22q12.2." (PMID 33445724, 2021). "Up to 60% of NF2 patients develop meningiomas, mostly benign and often multiple, which are associated with disease severity and increased mortality." (PMID 34604034, 2021). "Loss of chromosome 22q, where neurofibromatosis type 2 (NF2) gene is located is the most common chromosomal abnormality and is found in up to 80% of meningiomas." (PMID 33801089, 2021). "Mutations in NF2 occur in schwannomas and meningiomas, as well as other types of cancer including GBM, hepatic, mesothelioma, breast, colorectal, skin, clear cell renal cell carcinoma, and prostate cancer (Petrilli & Fernández-Valle, 2016)." (PMID 34301805, 2021). "While children with NF1 have an increased risk for developing low-grade optic pathway and brainstem gliomas, the NF2 typically associates with low-grade tumors of cranial nerves (vestibular schwannomas), meninges (meningiomas) and spinal cord (ependymomas)." (PMID 34325699, 2021). "Understanding the genomic and molecular pathogenesis of NF2-mutated meningiomas will provide insight into meningioma tumorigenesis as a whole and offer new avenues for efficacious therapies." (PMID 33445724, 2021). "The NF2-deficient meningioma cells exhibited senescence and reduced cell growth in comparison to matched normal arachnoidal cells or to NF2-expressing meningioma cells, and the same phenotype was obtained by silencing NF2 in normal arachnoidal cells." (PMID 31963394, 2020). "Mutations in SMARCB1 have been identified in a rarity of sporadic WHO grade 1 and 2 meningiomas, often colocalizing with NF2 mutations." (PMID 33346248, 2020). "Meningiomas with Neurofibromin 2 gene mutations (NF2-mutant meningiomas) account for ~40% of the sporadic meningiomas." (PMID 32642722, 2020).